ABCA1 (ATP binding cassette subfamily A member 1)
Diseases named in the same sentence as ABCA1 in open-access papers (continued):
Sharing a sentence is not in itself a finding about the gene and the disease.
Tangier disease (continued). "Mutations in hexaminidase A, hexaminidase B, Niemann-Pick type C2, and ATP-binding cassette transporter A1 (ABCA1) cause Tay-Sachs, Sandhoff disease, Niemann-Pick type C2 (NPC2), and Tangier disease, respectively." (PMID 24058676, 2013). "Tangier disease patients and ABCA1−/− mice fail to form discoid or spherical HDL, which exhibit abnormal lipid deposition in various tissues." (PMID 22078494, 2011). "Studies on Tangier disease have revealed an important role of ATP-binding cassette transporter A1 (ABCA1) in cholesterol homeostasis." (PMID 19718435, 2009). "Conversely, LXRs are unable to stimulate cholesterol efflux to lipid-poor lipoproteins in fibroblasts from Tangier disease patients, demonstrating that ABCA1 is essential for the LXR-mediated efflux pathway." (PMID 20046702, 2008). "Mutations in the cystic fibrosis transmembrane conductance regulator (CFTR) gene can cause cystic fibrosis, and mutations in ABCA1 and ABCA3 are responsible for respectively Tangier disease and fatal surfactant deficiency." (PMID 15967026, 2005). "Similarly, Tangier disease involves ABCA1 dysfunction, impairing cholesterol efflux and HDL formation, contributing to lipid imbalances." (PMID 40710499, 2025). "This notion is further corroborated by human data showing that diabetes is not a characteristic feature of Tangier disease (homozygous loss-of-function variants in ABCA1 gene) and by studies showing inconsistent association of ABCA1 gene variation with T2D." (PMID 38747290, 2024). "ABCA1 molecular gene sequencing is the gold standard for diagnosing Tangier disease." (PMID 36651718, 2023). "Tangier’s disease is a high-risk ASCVD disease due to the lack of ABCA1, leading to high TG and TC and low HDL." (PMID 36904298, 2023). "Whether plasma sphingolipids are reduced in Tangier disease and to what extent hepatic ABCA1 contributes to plasma sphingolipid (SL) levels is unknown." (PMID 37601634, 2023). "Since pancreatic β-cells express ABCA1, glucose-stimulated insulin secretion may be impaired in Tangier disease patients." (PMID 37233667, 2023). "Surprisingly, the amount of excreted sterols in the feces of Tangier disease patients or ABCA1-deficient mice remains normal, and they show no disturbance in whole-body cholesterol homeostasis." (PMID 35464770, 2022). "Importantly, the corresponding amino acid substitution of the conserved Alanine to Valine in ABCA1 (p.A937V) is responsible for Tangier disease and highlights the importance of this residue." (PMID 35361255, 2022). "Monoallelic mutations in ABCA1 are the cause of familial high-density lipoprotein (HDL) deficiency, whereas homozygous or compound heterozygous mutations represent a more severe phenotype known as Tangier disease." (PMID 35361255, 2022). "Second, four point mutations that cause Tangier disease (two shown not to affect cell-surface expression of ABCA1) are located in the loop (D571G, R587W, W590S/L)." (PMID 35974019, 2022). "The ABCA transporter family is involved in the transport of a variety of lipid substrates, some of them being associated with severe recessive human inherited disorders such as Tangier disease (ABCA1), Stargardt disease (ABCA4) or harlequin ichthyosis (ABCA12)." (PMID 34638622, 2021). "RPE of Tangier patients might be healthier compared to AMD-affected RPE, making the impact of dysfunctional ABCA1 weaker in Tangier disease." (PMID 30864945, 2019). "To test if the lipid floppase activity (outward translocation across the plasma membrane) of ABCA1 is required for increased cholesterol release in Miltefosine treated cells, we used HEK293 cells stably expressing WT-ABCA1 isoform or a Tangier disease double mutant W590S-C1477R-ABCA1 isoform." (PMID 31366948, 2019).
Tangier disease (continued). "The most important of these pathways involves the efflux of phospholipids and free cholesterol on to lipid-free or lipid-poor apolipoproteins via ABCA1, as demonstrated by the inability of ABCA1-knockout mice or patients with Tangier’s disease (who lack ABCA1) to generate HDL." (PMID 30675710, 2019). "ABCA1, which is defective in Tangier disease, is a key regulator of cholesterol efflux." (PMID 30496280, 2018). "Therefore, as in Tangier’s disease, the significant decrease in hepatic Abca1 likely accounts for the decreased plasma ApoA1 in the Lrp1Y63F mouse." (PMID 29144234, 2017). "Mutations in the ABCA1 gene cause Tangier disease and familial hypoalphalipoproteinemia which are characterized by a severe reduction in the amount of HDL, demonstrating ABCA1 as a critical molecule in regulating an initial step of reverse cholesterol transport." (PMID 27136542, 2016). "T2D is not a feature of Tangier disease, which is caused by recessive loss of function ABCA1 mutations." (PMID 26579206, 2015). "Misfolding and ER retention of other lipid ABC transporters of the A subfamily, as ABCA1 and ABCA4, cause Tangier disease and Stargardt macular dystrophy, respectively, but their influence on ER stress and apoptosis is unknown." (PMID 21214890, 2011). "Genetic absence of functional ATP binding cassette transporter A1 (ABCA1) in Tangier disease is associated with severely lowered plasma HDL and concomitantly elevated plasma TAG concentrations." (PMID 20423497, 2010). "Notably, we describe the first novel splice site error in the ABCA1 gene within an Ashkenazi Jewish population, where a tendency toward consanguinity suggests that other undiagnosed cases of Tangier disease may exist." (PMID 40476138, 2025). "Mutations in the ABCA1 gene lead to Tangier disease (lack of plasma HDL, premature CAD), and its polymorphisms may modulate blood lipid levels." (PMID 36421822, 2022). "A clinical report showed that four Japanese patients with Tangier Disease and T2D exhibited lower value of the insulinogenic index insulin compared to non-diabetic TD patients, indicating that cholesterol content and ABCA1 may be critical for insulin secretion." (PMID 34578896, 2021). "GSL biosynthesis inhibitor therapies (miglustat, eliglustat, and so on), may be particularly effective as it has been previously demonstrated that GSL accumulation can further inhibit ABCA1 expression, and in this way may have increased efficacy in Tangier disease patients." (PMID 31707734, 2020). "Whereas the identification of two intronic mutations in ABCA1, located on opposite chromosomes may have predicted the Tangier Disease phenotype, the patient did not exhibit any of the known clinical features of this disorder." (PMID 19133158, 2009). "Although the precise mechanism leading to the secondary induction of NPC cellular phenotypes in Tangier disease cells remains to be determined, this unexpected finding reinforces the links between NPC1 and ABCA1 function." (PMID 37844193, 2023). "Furthermore, biallelic mutations in the coding region of ABCA1 cause the very rare Tangier disease characterized by a virtual absence of plasma HDL and ApoAI and the presence of cholesterol-laden macrophages in various tissues, including tonsils, spleen and bone marrow." (PMID 35328615, 2022). "In this regard, ABC transporters, such as ABCA1, ABCG5 and ABCG8, were initially found to be responsible for genetically-inherited syndromes like Tangier diseases and sitosterolemia." (PMID 28383515, 2017). "The absence of ABCA1 gene will result in Tangier disease characterized with lipid metabolism disorder and absent HDL levels in human." (PMID 36387364, 2022). "Despite the high homology between ABCA1 and ABCA7, the latter does not compensate for the loss of ABCA1 in Tangier disease patients, further questioning the exact role of ABCA7 in cellular cholesterol release." (PMID 35477481, 2022).
Tangier disease (continued). "The absence of efflux activity in fibroblasts from a patient with Tangier disease, and the absence of an increase in ABCA1 mRNA, revealed a new mechanism of action." (PMID 34341345, 2021). "Although glaucoma is not a characteristic of Tangier disease, GWAS for IOP and POAG have identified common variants in or near ABCA1 (rs2472493 and rs2487032) among more than 50 loci in Asian and European Caucasian populations." (PMID 33562440, 2021). "The defects of ABCA1 gene leads to Tangier disease, which is characterized by extreme lack of HDL cholesterol in plasma, obstacles of cholesterol efflux and a great amount cholesterol deposition in peripheral tissue." (PMID 25329888, 2014). "The absence of functional ABCA1 is the feature of Tangier disease, characterized by a severely impaired lipidation of ApoA1 via the ABCA1 pathway, and very low blood levels of HDL." (PMID 24646941, 2014). "Both human patients with nonfunctional ABCA1 due to autosomal recessive disorder (Tangier disease) and ABCA1 knockout mice showed extremely low plasma HDL levels, underscoring the importance of ABCA1 in HDL metabolism." (PMID 19636418, 2009). "Mutations in the human ABCA1 gene cause Tangier disease, in which patients exhibit little or no plasma HDL and prominent cholesterol deposition in peripheral tissues, indicating the functional relevance of ABCA1 in RCT." (PMID 26452260, 2015). "Efflux activity of ABCA1 initiates HDL assembly and defects in ABCA1-mediated cholesterol efflux lead to nearly non-detectable plasma HDL cholesterol (HDLc) levels in the mouse or Tangier disease in humans." (PMID 29069761, 2017).
dyslipidemia (66 papers, 2009 to 2025). "In diabetic or dyslipidemic populations, novel variants (e.g., rs2066714 and rs757194699) are linked to increased susceptibility to dyslipidemia through altered ABCA1-apoA1 interaction and impaired lipid efflux capacity." (PMID 41226793, 2025). "They reported an elevated risk of coronary artery disease with dyslipidemia in the Chinese population for the carriers of the ABCA1 rs4149339 genotype CC." (PMID 39596349, 2024). "The G allele of rs2066714 and C allele of rs757194699 in the ABCA1 gene were found to be risk alleles in the development of dyslipidemia in type 2 diabetes." (PMID 38928502, 2024). "Dyslipidemias, hepatic steatosis index, and ABCA1 (rs1800977) gene polymorphism CC genotype; were the only independent predictors of advanced fibrosis in NAFLD‐patients." (PMID 36444680, 2023). "Our data showed that ABCA1 deficiency resulted in dyslipidemia and increased inflammation in mice, and that ABCA1 knockdown promoted increased inflammatory levels in RAW 264.7 cells." (PMID 36904298, 2023). "The findings suggest that diabetes mellitus is associated with dyslipidemia through diminished ABCA1 gene expression." (PMID 37821518, 2023). "Recent studies on different populations have observed an association of ABCA1 C69T polymorphism with the risk of dyslipidemia in diabetic individuals." (PMID 36553543, 2022). "Dyslipidemia is highly prevalent in the Mexicans, which is consistent with the association of the ABCA1/R230C variant with T2D in this population." (PMID 33562440, 2021). "VEGF induced angiogenesis combined with dyslipidemia due to ABCA1 polymorphisms will inevitably lead to retinopathy." (PMID 35069435, 2021). "The rising levels of cholesterol in the case of ABCA1 mutations leading to various SNPs and thus, variable protein product expression will inevitably lead to dyslipidemia, renal insufficiency, and diabetic nephropathy." (PMID 35069435, 2021). "The Nef protein causes dyslipidemia, as it affects cholesterol efflux by reducing the expression of ABCA1 in in vitro and in vivo models." (PMID 33562440, 2021). "In this study, ABCA1 (rs2066714) G/G genotype was associated with an increased probability of having dyslipidemia." (PMID 31929604, 2020). "Studies have demonstrated that the ABCA1 rs2230806 polymorphism is significantly associated with patients with severe dyslipidemia, such as coronary heart disease and obesity, as well as with DM." (PMID 33426085, 2020). "The aim of our study was to determine the associations of ABCA1 gene polymorphisms with the risks of diabetes mellitus and dyslipidemia in diabetic patients." (PMID 31010439, 2019). "Meanwhile, an association of ABCA1 rs2472386 with CAD was found in dyslipidemia only in male subjects." (PMID 30836684, 2019). "This indicates that the T mutation site of ABCA1 rs4743763 is a risk factor for CAD in dyslipidemia, and it is a newly identified SNP for susceptibility to coronary heart disease in the Chinese population." (PMID 30836684, 2019). "Some scholars have reported that the polymorphism of ABCA1 gene is not only associated with lipid metabolism, but also with other metabolic diseases such as type 2 diabetes, obesity and metabolic syndrome." (PMID 26891315, 2016). "Previous work from our group and others has shown that ABCA1 DNA methylation is associated with aging, dyslipidemia and CAD." (PMID 25093045, 2014). "Low plasma HDL is associated with type 2 diabetes and metabolic syndrome suggesting that ABCA1 contributes to this complication." (PMID 20030852, 2009). "However, there are no published studies carried out on Saudi individuals investigating the association between ABCA1 C69T gene polymorphism and the risk of dyslipidemia in prediabetics or undiagnosed diabetic individuals." (PMID 36553543, 2022).
dyslipidemia (continued). "It is well-known that ABCA1/ABCG1 plays a central role in reverse cholesterol transport (RCT); the dysfunction of ABCA1/ABCG1 caused by the rs2910164 polymorphism may therefore result in dyslipidemia." (PMID 34646311, 2021). "A polymorphic ABCA1 is thus associated with albuminuria, dyslipidemia, and hypertensive crises." (PMID 35069435, 2021). "Therefore, we performed the pooled analysis to evaluate the relationships between the ABCA1 gene polymorphisms and the risks of diabetes and dyslipidemia in diabetic patients." (PMID 31010439, 2019). "Within this context, the ABCA1 genotype functions as a modifier of lipid burden and lipid-driven neurodegeneration: individuals carrying disadvantageous ABCA1 variants in the presence of dyslipidemia are at increased risk of cholesterol-induced neuronal pathology." (PMID 41226793, 2025). "Therefore, we aimed to investigate the prevalence of ABCA1 C69T (rs1800977) gene polymorphism in a representative sample of the Saudi population not previously diagnosed with diabetes and its possible association with dyslipidemia and dysglycemia." (PMID 36553543, 2022). "This highlights the fact that hypoalphalipoproteinemia is the main dyslipidemia detected in the Mexican population, partly as a consequence of the high prevalence of polymorphisms in the CETP, APOA1, and ABCA1 genes." (PMID 37892400, 2023). "The independent t test results were statistically significant (p = ≤ 0.05) when observed in relation with ABCA1 Ct and fold change among only diabetics and diabetics with dyslipidemia as compared to normal healthy." (PMID 37821518, 2023). "The present study showed that ABCA1 knockout resulted in dyslipidemia and increased inflammation in mice, which also resulted in significant fasting weight loss in the C8:0, C16:0, and EPA groups." (PMID 36904298, 2023). "The downregulation of ABCA1 expression was observed more in diabetics with dyslipidemia group as compared to only diabetics and healthy control groups." (PMID 37821518, 2023). "The aim of this research was to investigate the expression analysis of ABCA1 gene in Pakistani population and to find its correlation with glycemic status and lipid profile of diabetics, diabetics with dyslipidemia and healthy controls." (PMID 37821518, 2023). "Our findings exhibited diminished levels of ABCA1 correlated with that of lipid profile and fasting blood sugar among subjects with dyslipidemia." (PMID 37821518, 2023). "ABCA1 gene expression was more downregulated in diabetics with dyslipidemia as compared to only diabetics and healthy controls." (PMID 37821518, 2023). "Supporting these findings, polymorphisms in ATP-binding cassette transporter 1 gene (ABCA1), involved in cholesterol efflux and HDL synthesis, have been associated to obesity, the metabolic syndrome, and DM." (PMID 35406116, 2022). "It is worth mentioning that ABCA1 is also associated with glucose uptake by GLUT4 in skeletal muscles, and the aberration of ABCA1-regulated phenotypes is recognized in metabolic syndrome patients." (PMID 36271927, 2022). "Therefore, the aim of the present study was to investigate the prevalence of ABCA1 C69T (rs1800977) gene polymorphism in a randomly collected representative sample of the Saudi population not previously diagnosed with diabetes and its possible association with dyslipidemia and dysglycemia." (PMID 36553543, 2022). "In conclusion, polymorphisms of rs4149339, rs4743763 and rs2472386 in ABCA1 and three lifestyle factors (physical activity, fried food intake, and dessert intake) were found to be associated with CAD in people with dyslipidemia in southern China." (PMID 30836684, 2019). "The association between the ABCA1 gene and lifestyle factors with CAD in dyslipidemia was examined under each gene model." (PMID 30836684, 2019).